CELSR3 (cadherin EGF LAG seven-pass G-type receptor 3)
Diseases named in the same sentence as CELSR3 in open-access papers (continued):
Sharing a sentence is not in itself a finding about the gene and the disease.
tumor (18 papers, 2010 to 2024). "The purpose of this study was to look at the diagnostic significance of the CELSR3 gene in HNSCC as well as its effect on tumor immune invasion." (PMID 38507078, 2024). "CELSR3 has been linked to tumor immune cell infiltration, immunological checkpoints, and immune-related genes." (PMID 38507078, 2024). "CELSR3 expression is elevated in HNSCC tumor tissues, and high CELSR3 expression is associated with well prognosis, which inhibited the proliferation of NHSCC cells." (PMID 38507078, 2024). "We found that CELSR3 expression is elevated in HNSCC tumor tissues, and high CELSR3 expression is associated with well prognosis, which inhibited the proliferation of NHSCC cells." (PMID 38507078, 2024). "For example, cadherin EGF LAG seven-pass G-type receptor 3 (CELSR3) was 3.04-fold upregulated in tumor associated stellate cells compared to inflammation associated stellate cells." (PMID 20416094, 2010). "Furthermore, the expression of CELSR3 was significantly increased in mCRPC compared to primary PCa, and this expression pattern was associated with tumor progression (P < 0.001)." (PMID 33442409, 2021). "Univariate analysis showed that high expression of CELSR3 mRNA was significantly correlated with poor overall survival and other variables associated with a reduced overall survival rate, including tumor status, stage, T stage, N stage, M stage, and residual tumor." (PMID 31608178, 2019). "Importantly, expression of CELSR3 in BMDC associated with tumor suggests that there was modification of these PaSC's by the tumor microenvironment." (PMID 22022519, 2011). "CELSR3 has the potential to influence tumor formation by controlling tumor-infiltrating cells in the tumor microenvironment (TME)." (PMID 38507078, 2024). "In conclusion, our findings show that CELSR3 expression is enhanced in HNSCC tumor tissues, and that high CELSR3 expression is related to well prognosis." (PMID 38507078, 2024). "CELSR3 has the potential to influence tumor formation by controlling tumor-infiltrating cells in the TME." (PMID 38507078, 2024). "The correlation between CELSR3 and tumor immune cell infiltration, immune checkpoint, immune-related genes, and immune checkpoint blockade (ICB) was detected." (PMID 38507078, 2024). "We used Spearman’s correlation to reveal a link between CELSR3 expression levels and immune cell infiltration levels assessed by ssGSEA in the HCC tumor microenvironment to investigate the effect of CELSR3 expression on the tumor microenvironment." (PMID 38507078, 2024). "We used Spearman’s correlation to reveal a link between CELSR3 expression levels and immune cell infiltration levels assessed by ssGSEA in the HCC tumor microenvironment to better understand the effect of CELSR3 expression on the tumor microenvironment." (PMID 38507078, 2024). "On the basis of this dataset, we found that both Hmmr and Celsr3 were expressed at significantly higher levels in the differentiated/NEPC tumor foci compared with the adenocarcinoma tumor foci." (PMID 37546702, 2023). "Hits were triaged in biophysical and cellular assays and several potent binders identified and expressed as bispecific mAbs (bs-mAb) designed to simultaneously bind to CELSR3 on a tumor cell and the CD3 receptor present on human T cells." (PMID 37546702, 2023). "We further showed that cadherin EGF LAG seven-pass G-type receptor 3 (CELSR3) knockdown results in reduced NEPC tumor cell proliferation and migration in vitro." (PMID 37546702, 2023). "Consistent with this, we also found that tumors with reduced levels of CELSR3 displayed a variety of tumor histologies including regions of small cell/NEPC cells and regions that harbored luminal/gland-like structures." (PMID 37546702, 2023). "To understand the mechanisms of how CELSR3 regulate tumour development, invasion and metastasis in LUAD, we examined the associated transcription factors and kinases." (PMID 33811453, 2021).
tumor (continued). "We identified eight overexpressed and mutated tumor antigens with poor prognostic value of PRAD, including KLHL17, CPT1B, IQGAP3, LIME1, YJEFN3, KIAA1529, MSH5 and CELSR3." (PMID 34872584, 2021). "In summary, kinases and transcription factors related to CELSR3 are closely related to the proliferation, cell cycle, invasion and metastasis of tumour cell." (PMID 33811453, 2021). "Our findings have revelled that CELSR3 down‐regulation significantly suppressed cell proliferation and markedly suppressed tumour growth in vitro." (PMID 33811453, 2021). "We illuminated the upregulated CELSR3 in HCC was correlated to tumor size, pathological stage, and poor survival." (PMID 32226501, 2020). "Regarding liver cancer, scholars have reported that CELSR3 was up-regulated in tumor stellate cells." (PMID 32226501, 2020). "Elevated CELSR3 was correlated to the bigger tumor size, higher pathological stage, and the worse overall survival of HCC." (PMID 32226501, 2020). "Based on the action mechanism of miRNA on mRNA and putative oncogenic roles of CELSR3, GPSM2, and CHEK1, potential miRNAs should be tumor suppressive miRNAs and should be negatively correlated with CELSR3, GPSM2, or CHEK1." (PMID 32257949, 2020). "Multivariate analysis using the Cox proportional hazards model indicated that high expression of CELSR3 mRNA (HR = 1.88, P = 0.004) and residual tumor (HR = 1.36, P = 0.033) were independent prognostic factors for the overall survival of HCC patients." (PMID 31608178, 2019). "By immunoblot analysis, CELSR3 protein was expressed at 83% higher levels (p = 0.030) in tumor related stellate cells compared to that of inflammation related stellate cells." (PMID 20416094, 2010). "Intriguingly, tyrosine kinase JAK2 and a member of cell contact-mediated communication CELSR3 were found to be selectively up-regulated in tumor stellate cells." (PMID 20416094, 2010). "Together, these data suggest an important role for CELSR3 in tumor stellate cells that warrants further investigation." (PMID 20416094, 2010). "Taken together, CELSR3’s influence on immune cell infiltration has a good impact on tumor patients." (PMID 38507078, 2024). "In all, CELSR3 was found to be an oncogene that promoted malignant progression of the tumor." (PMID 33442409, 2021). "Furthermore, patients with LUAD showing high CELSR3 expression compared with the median level were predicted to have poor prognosis and early tumour progression." (PMID 33811453, 2021). "In addition, we explored the relationship between CELSR3 mRNA expression levels and clinical subgroups and tumour‐infiltrating immune cells in patients with LUAD." (PMID 33811453, 2021). "A high expression of CELSR3 indicated a more advanced tumor size and pathological stage." (PMID 32226501, 2020). "Moreover, CELSR3 was found to be significantly correlated with the tumor size, pathological stage, and cancer status." (PMID 32226501, 2020). "Moreover, there were also different CELSR3 expression levels in the groups classified according to age (P = 0.023), tumor status (P = 0.030), stage (P = 0.023), and vital status (P = 0.027)." (PMID 31608178, 2019). "The relationship between CELSR3 mRNA expression and clinical features indicated that CELSR3 mRNA expression was significantly correlated with age (P = 0.025), tumor status (P = 0.022), clinical stage (P = 0.003), T classification (P = 0.010), vital status (P = 0.001), and relapse (P = 0.005)." (PMID 31608178, 2019). "Upregulation of CELSR3 in tumor PSC could also provide a potential druggable target since the protein encoded by this gene is located at the plasma membrane and has intriguing signaling capabilities." (PMID 20416094, 2010). "Finally, we can conclude that CELSR3 may be involved in tumor formation and development by influencing cell proliferation via the cellular microenvironment." (PMID 38507078, 2024).
tumor (continued). "High-risk prognostic genes BMP4, CELSR3, GPRC5C, and RUNDC3B, highly expressed in Epithelial Cells, CCBE1 showed expression in Leydig cells, SCGB2A2 highly expressed in Epithelial Cells and Cancer cells, suggesting that Epithelial cell play an important role in tumor growth and initiation." (PMID 37985782, 2023). "Therefore, the identified tumor stellate cell specific genes e.g. CELSR3 might provide a favorable therapeutic profile to selectively target tumor stroma while sparing the stellate cell activity under physiological conditions." (PMID 20416094, 2010). "The results indicated that CELSR3 is highly expressed in HCC tissues, and the expression of CELSR3 was high in older patients, in those with advanced tumor status or TNM stage III, and in those who had died." (PMID 31608178, 2019). "The expression of CELSR3 mRNA was upregulated in HCC, and its expression was correlated with age (P = 0.025), tumor status (P = 0.022), clinical stage (P = 0.003), T classification (P = 0.010), vital status (P = 0.001), and relapse (P = 0.005)." (PMID 31608178, 2019). "Among the here identified tumor stellate cell specific genes, JAK2 and CELSR3 pose interesting targets for developing therapeutic strategies." (PMID 20416094, 2010). "Several bioinformatics tools were employed to investigate CELSR3’s putative oncogenic pathway in HNSCC, and datasets from The Tumor Genome Atlas (TCGA), Tumor Immune Estimation Resource (TIMER), Gene Expression Profile Interaction Analysis (GEPIA) and LinkedOmics were extracted and evaluated." (PMID 38507078, 2024). "The Tumor Genome Atlas (TCGA), Tumor Immune Estimation Resource (TIMER), Gene Expression Profile Interaction Analysis (GEPIA), and LinkedOmics datasets were extracted and analyzed in this study to explore the potential oncogenic mechanism of CELSR3 in HNSCC." (PMID 38507078, 2024). "CDCA7, CELSR3, PACS1, SNTB1, and TBC1D31 showed consistent upregulation in CRC tumor samples and pre-surgical cfRNA, while GFI1B, HPGD, SH3BGRL2, SIAE, PKHD1L1, and TDP2 showed downregulation in CRC tumor samples and pre-surgical cfRNA." (PMID 37091184, 2023). "Although, we found that the sgCELSR3 decreased organoid growth in vitro comparing with sgGFP control, there was no significant impact on tumor growth or metastatic potential upon CELSR3 KO." (PMID 37546702, 2023). "In vivo, although reduction of CELSR3 did not impact NEPC tumor growth rate or metastatic potential, we did find that reduction of CELSR3 resulted in a diminution of NEPC markers (e.g., SYP, ASCL1, INSM1, SYP, and CHGA) in vitro and in vivo." (PMID 37546702, 2023). "In contrast, MAP2K7, CELSR3, and PFKP were overexpressed in tumor tissues." (PMID 36339718, 2022). "Furthermore, CELSR3‐related functional classification and the KEGG pathway are closely related to tumour development, invasion and metastasis." (PMID 33811453, 2021). "High expression of CELSR3 is in LUAD predicts poor prognosis and early progression of the tumour." (PMID 33811453, 2021). "Four missense variants were heterozygous in the tumor sample and not present in blood (FAM117B, CTNNB1, CELSR3 and STXBP5L)." (PMID 33379206, 2020). "Furthermore, cytokine and immune checkpoint blockade therapy have become treatment options for a variety of cancers, but no research has been conducted to determine whether CELSR3 overexpression influences the tumor immune microenvironment in HNSCC." (PMID 38507078, 2024). "Although, the lack of an available antibody did not allow for the examination of CELSR3 protein expression in patient tumors, we showed that CELSR3 knockdown results in reduced NEPC tumor cell proliferation and migration in vitro." (PMID 37546702, 2023).
cancer (15 papers, 2011 to 2024). A tumor composed of atypical neoplastic, often pleomorphic cells that invade other tissues. "CELSR3 has been linked to a variety of cancers, including hepatic, prostate, and lung adenocarcinomas." (PMID 38507078, 2024). "CELSR3 expression was similarly higher in cancer tissues than in matched normal neighboring tissue samples in the 43 pared samples." (PMID 38507078, 2024). "CELSR3 expression was discovered to be differentially expressed in numerous forms of cancer and their matching normal tissues in our investigation, including BLCA, BRCA, CHOL, COAD, ESCA, KIRC, and others." (PMID 38507078, 2024). "CELSR3, GPR25, EDNRB, and F2RL2 are significantly associated with patients’ survival in four cancers each, with an equal prevalence for lower and higher survival." (PMID 38723607, 2024). "The mRNA expression level of CELSR3 was highest in the 22RV1 cell line compared to other cancer cell lines, which was also consistent with the highly malignant characteristics of this cell line." (PMID 33442409, 2021). "Although some members of the CELSR family have been shown to play a key role in cancer, the exact roles of CELSR3 in LUAD remained unclear." (PMID 33811453, 2021). "Our results indicate that CELSR3 mRNA is involved in the progression of cancer and can be used as a biomarker for the prognosis of HCC patients." (PMID 31608178, 2019). "CELSR3 was shown to be expressed differently in different types of cancer and normal tissues." (PMID 38507078, 2024). "Moreover, CELSR3 was suggested to be involved in the progression of cancer and can be used as a biomarker for the prognosis of HCC patients directly." (PMID 34386813, 2021). "CELSR3 is expressed in Epithelial Cells, CT83 is highly expressed in Cancer cells, Epithelial cells, and Neutrophils, and CXCL11 is expressed in Fibroblast and M1 Macrophages." (PMID 37985782, 2023). "The Cancer Genome Atlas (TCGA) database, the Cancer Cell Line Encyclopedia (CCLE) database and the Gene Expression Omnibus (GEO) database were used to analyze the expression of CELSR3 mRNA in HCC samples and cells." (PMID 31608178, 2019). "CELSR3, TRPM2, and TRIP13 are over-expressed in all the 13 cancers, TNXB is under-expressed in all the 13 cancers, KCNAB1 is over-expressed in KIRC but under-expressed in the other 12 cancers." (PMID 30729033, 2019). "Besides cancer-related genes, three genes ARL14, CELSR3, and WFDC3 are also observed in our list." (PMID 27610367, 2016).
neurodevelopmental disorder (2 papers, 2020 to 2022). A behavioral and cognitive disorder with onset during the developmental period that involves impaired or aberrant development of intellectual, motor, or social functions. "Other genes, such as GMIP, NEK1, TFPT, CELSR3, and TTC21A, also showed interactions with ASD or other neurodevelopmental disorder-related genes in each gene network in the previous studies." (PMID 33374967, 2020).
CELSR3 also shares sentences with these, for which no sentence is quoted: breast carcinoma (4 papers); ovarian carcinoma (3); adenocarcinoma (2); bladder urothelial carcinoma (2); head and neck squamous cell carcinoma (2); aortic stenosis (1); autism spectrum disorder (1); B-cell lymphoma (1); cervical cancer (1); cholangiocarcinoma (1); cloacal exstrophy (1); CNS lymphoma (1); colon adenocarcinoma (1); congenital heart defects (1); congenital megacolon (1); developmental delay (1); febrile seizures (1); fibrosis (1); gastric cancer (1); genetic disease (1); glioma (1); Hepatic steatosis (1); idiopathic scoliosis (1); infection (1); laryngeal carcinoma (1); liver fibrosis (1); lymphoma (1); male infertility (1); melanoma (1); metastatic melanoma (1).
A further 2 diseases each share a sentence with CELSR3 in 1 paper.